SLC25A44 (solute carrier family 25 member 44)
Description:
Mitochondrial solute transporter which transports branched-chain amino acid (BCAA; valine, leucine and isoleucine) into mitochondria in brown adipose tissue (BAT) (By similarity). BAT is involved in BCAA catabolism and actively utilizes BCAA in the mitochondria for thermogenesis.
Synonyms: KIAA0446; FLJ90431
Tractability: Antibody: UniProt predicts a signal peptide or a membrane-spanning region. PROTAC: its protein half-life has been measured.
Gene: Protein-coding gene on chromosome 1 (156,193,932 to 156,212,796, forward strand). Ensembl gene ENSG00000160785.
Subcellular location: Mitochondrion membrane
Subcellular location (Human Protein Atlas): Mitochondria; Nucleoplasm
Pathways (Reactome):
Metabolism: Branched-chain amino acid catabolism
Gene Ontology:
Molecular function: branched-chain amino acid transmembrane transporter activity
Biological process: branched-chain amino acid catabolic process; branched-chain amino acid transport; regulation of cold-induced thermogenesis; transmembrane transport
Cellular component: mitochondrion; mitochondrial membrane; mitochondrial inner membrane
Genetic constraint (gnomAD): Loss-of-function variants: 17 observed, 29.79 expected, observed/expected ratio (o/e) 0.57, 90% interval 0.39 to 0.86. The upper end of that interval is the gene's LOEUF score, 0.86, which puts it in group 3 of 6, group 1 being the genes least tolerant of losing a copy. Missense variants: 302 observed, 414.73 expected, observed/expected ratio (o/e) 0.73, 90% interval 0.66 to 0.8. Synonymous variants: 140 observed, 159 expected, observed/expected ratio (o/e) 0.88, 90% interval 0.77 to 1.01.
Homologues: Orthologues: chimpanzee SLC25A44 (100% identical), pig SLC25A44 (98% identical), rabbit SLC25A44 (98% identical), dog SLC25A44 (97% identical), mouse Slc25a44 (96% identical), rat Slc25a44 (96% identical), guinea pig SLC25A44 (90% identical), tropical clawed frog slc25a44 (85% identical), macaque BGLAP (84% identical), zebrafish slc25a44b (75% identical), zebrafish slc25a44a (73% identical), Drosophila melanogaster CG5805 (39% identical), and 1 more. Paralogues in human: SLC25A12 (26% identical), SLC25A13 (25% identical), SLC25A1 (24% identical), SLC25A37 (23% identical), SLC25A22 (22% identical), SLC25A25 (22% identical), SLC25A18 (21% identical), SLC25A28 (21% identical), SLC25A14 (21% identical), SLC25A23 (21% identical), SLC25A24 (21% identical), SLC25A30 (21% identical), and 37 more.
Diseases named in the same sentence as SLC25A44 in open-access papers:
SLC25A44 is named in the same sentence as 16 diseases in open-access papers, as found by Europe PMC text mining. Sharing a sentence is not in itself a finding about the gene and the disease. The quoted sentences say what the papers report.
Obesity (2 papers, 2021 to 2023). Accumulation of substantial excess body fat. "Activation of BCAA catabolism can induce adaptive thermogenesis in response to cold shock in brown adipose tissues, where SLC25A44 actively transports BCAAs into mitochondria, improving diet-induced obesity and glucose intolerance." (PMID 37648026, 2023). "We have previously reported that BCAA catabolism in BAT is mediated by SLC25A44 for thermogenesis and that BAT plays an important role in systemic BCAA clearance and protects against obesity and insulin resistance." (PMID 34805797, 2021).
Stroke (2 papers, 2019 to 2022). Sudden impairment of blood flow to a part of the brain due to occlusion or rupture of an artery to the brain. "SLC25A44 is a gene on locus 1q22 and encodes a mitochondrial carrier protein, suggesting that stroke may be associated with mitochondrial dysfunction." (PMID 31392102, 2019). "Besides, two genes (SLC25A44 and LRCH1), whose expression were significantly associated with stroke after Bonferroni correction, were identified as candidate genes in a recent TWAS in adipose." (PMID 35449099, 2022). "SLC25A44 and LRCH1 were the only two genes passing the Bonferroni correction threshold (P < 0.05/11,826) for all gene-stroke features, which implied that they were strongly associated with stroke." (PMID 31392102, 2019). "Our TWAS identified two genes, i.e., SLC25A44 and LRCH1, that were significant for stroke after Bonferroni correction." (PMID 31392102, 2019). "The TWAS identified 515 transcriptome-wide significant tissue-specific genes, among which SLC25A44 (P = 5.46E−10) and LRCH1 (P = 1.54E−6) were significant by Bonferroni test for stroke." (PMID 31392102, 2019).
cerebrovascular diseases (1 paper, 2022). "Recent studies have shown that SLC25A44 is associated with cerebrovascular diseases." (PMID 36514121, 2022).
hemorrhagic stroke (1 paper, 2017). A stroke caused by a bleed on the brain. "Genome-wideassociation studies have identified several single nucleotide polymorphisms (SNPs)associated with sporadic hemorrhagic strokes, including APOE(19q13), SLC25A44 (1q22), COL4A1 (13q34) andKCNK17 (6p21)." (PMID 28153846, 2017).
maturity-onset diabetes (1 paper, 2022). "SLC25A44 and its positively correlated genes, on the contrary, were enriched in pathways related to the synaptic vesicle cycle, nicotine addiction, maturity-onset diabetes of the young, and synaptic vesicle recycling." (PMID 36514121, 2022).
meningioma (1 paper, 2023). A generally slow growing tumor attached to the dura mater. "Interestingly, seven of the meningioma-associated antigens were shared between all WHO grades (NMA2, TBX15/18, XXLT1, SLC25A44, RHOD, CREBL2, and PLCD4)." (PMID 37368072, 2023).
tumor (2 papers, 2021 to 2022). "The correlation between SLC25A11, SLC25A29, and SLC25A44 mRNA expression levels and tumor immune invasion was further explored in PC." (PMID 36514121, 2022). "According to co-expression network studies, SLC25A11, SLC25A29, and SLC25A44 were involved in the energy metabolism of PC and prevented tumor growth, invasion, and metastasis." (PMID 36514121, 2022). "For example, solute carrier family 25 member 44 is a mitochondrial branched-chain amino acid transporter and is part of a signalling network that provides important nutrients for tumour cell proliferation." (PMID 34832109, 2021). "Interestingly, SLC25A11, SLC25A29, and SLC25A44 were significantly overexpressed in ductal, acinar and endocrine cells in tumor tissues compared with normal tissues (P < 0.001)." (PMID 36514121, 2022). "SLC25A members are crucial for tumor immune and energy metabolism in PC, and SLC25A11, SLC25A29, and SLC25A44 can be used as favorable prognostic markers." (PMID 36514121, 2022). "As shown, of the various tumor pathological grades, the expression levels of SLC25A4 (P < 0.01), SLC25A11 (P < 0.0001), SLC25A24 (P < 0.01), SLC25A37 (P < 0.01), SLC25A42 (P < 0.01), SLC25A43 (P < 0.0001), SLC25A44 (P < 0.05) and SLC25A45 (P < 0.05) were significantly different." (PMID 36514121, 2022).
cancer (1 paper, 2022). A tumor composed of atypical neoplastic, often pleomorphic cells that invade other tissues. "Although the mechanism of SLC25A44 in cancer is unclear, our study found that its expression in PC is negatively correlated with various cancer pathways." (PMID 36514121, 2022).
metabolic disease (1 paper, 2021). A congenital disorder (due to inherited enzyme abnormality) or acquired (due to failure of a metabolically important organ) disorder resulting from an abnormal metabolic process. "SLC25A44 has an important role in catabolism of branched-chain amino acids in brown adipose tissue by transporting them into mitochondria, and thus has potential as a mediating factor in the relationship between metabolic disease and lacunar stroke." (PMID 33773637, 2021).
SLC25A44 also shares sentences with these, for which no sentence is quoted: colon cancer (1 paper); COVID-19 (1); Glucose intolerance (1); Insulin resistance (1); intracerebral hemorrhage (1); nicotine addiction (1); psoriasis (1).